C3 (complement C3)
Diseases named in the same sentence as C3 in open-access papers (continued):
Sharing a sentence is not in itself a finding about the gene and the disease.
endophthalmitis (1 paper, 2024). An infectious process affecting the internal structures of the eye. "C5 inhibition might have a potentially lower risk of endophthalmitis, preserving C3-associated effector functions, such as C3b-mediated opsonization and immune cell activation, compared to an upstream C3 blockade, which also abrogates C3b effects." (PMID 39338244, 2024).
erythema multiforme (1 paper, 2025). Erythema multiforme (EM) refers to a group ofhypersensitivity disorders characterized by symmetric red, patchy lesions, primarily on the arms and legs. "Nonetheless, we cannot exclude the possibility that this case could be the result of a minor erythema multiforme with IgA-positive DIF, although most positive DIF results appear to show IgM or C3 linear deposition in erythema multiforme." (PMID 40125011, 2025).
fibrosarcoma (1 paper, 2019). A malignant mesenchymal fibroblastic neoplasm affecting the soft tissue and bone. "PTX3 overexpression resulted in a significant reduction in the levels of C3 immunoreactivity in fibrosarcoma grafts." (PMID 31533326, 2019). "Indeed, we show that PTX3 reduces the level of complement 3 (C3) deposition reducing fibrosarcoma progression." (PMID 31533326, 2019).
food allergy (1 paper, 2022). Gastrointestinal disturbances, skin eruptions, or shock due to allergic reactions to allergens in food. "Within these, 113 genes (27.8%) have been previously associated with food allergy; within the top 10 DE genes, 8 genes have been previously linked to food allergy—C3, CXCL8, RARRES1, CXCL6, MUC5AC, CXCL1, and SAA3." (PMID 36452260, 2022).
Gliosis (1 paper, 2025). Gliosis is the focal proliferation of glial cells in the central nervous system. "In gliosis, C3 and LCN2 genes, identified as reactive markers due to their complement activation, doubled in expression compared to senescence." (PMID 40719049, 2025).
GNE myopathy (1 paper, 2022). "C1q and C3 were elevated in both axonal and demyelinating CMT patients sera, as well as GNE myopathy, compared with controls." (PMID 35148379, 2022).
hemangiosarcoma (1 paper, 2021). "C3 is an innate immune response protein that is released from the liver during inflammation and was elevated in hemangiosarcoma." (PMID 34065028, 2021).
hemophilia (1 paper, 2020). Hemophilia is a genetic disorder characterized by spontaneous hemorrhage or prolonged bleeding due to factor VIII or IX deficiency. "Similar to C3 knockout mice, B6 or hemophilia A mice that received nCVF prior to fVIII injection produced inhibitors at the same level as control mice." (PMID 32582142, 2020).
hemophilia A (1 paper, 2020). The most common form of hemophilia characterized by spontaneous or prolonged hemorrhages due to factor VIII deficiency. "As C3 knockout mice have normal levels of mouse fVIII, we next aimed to investigate the role of complement in FVIII-deficient hemophilia A mice." (PMID 32582142, 2020).
hemorrhagic stroke (1 paper, 2024). A stroke caused by a bleed on the brain. "Collectively, our data not only provide direct evidence for the involvement of plasma C3 levels in brain injury after hemorrhagic stroke but also suggest a new therapeutic approach for this disease." (PMID 38532579, 2024). "In the present study, we observed that plasma C3 levels increased as a result of hemorrhagic stroke, not only in ICH patients but also in hemorrhagic mice." (PMID 38532579, 2024). "Here, we reported that hemorrhagic stroke led to the activation of microglia and a remarkable increase in C3 expression levels in microglia, whereas NBO treatment significantly reduced C3 levels, which reflects decreased brain damage in these patients and animals." (PMID 38532579, 2024).
hemostatic disorders (1 paper, 2024). "Additionally, a decrease in intact C3 levels was also correlated with uncontrolled systemic and pulmonary inflammation and hemostatic disorders, thus indicating that complement can act mutually with other systems in diverse diseases, including in bee envenomation." (PMID 39606222, 2024).
Hepatic hemangioma (1 paper, 2025). A congenital vascular malformation in the liver composed of masses of blood vessels that are atypical or irregular in arrangement and size. "Furthermore, the white blood cell count, CRP, C3, C4, CH50, and ESR improved, suggesting that the unknown fever might have been caused by the necrotic area of the hepatic hemangioma." (PMID 40404957, 2025).
hereditary glaucoma (1 paper, 2024). Hereditary glaucoma is a clinically diverse group of rare eye disorders with genetic predisposition characterized by elevated intraocular pressure (IOP) and glaucomatous changes of the optic nerve head, leading to field defects, visual loss and blindness. "For example, transgenic targeting of complement C3 delayed the progression of neurodegeneration in mice with hereditary glaucoma; however, C3 induced neuroprotective functions of astrocytes at early disease stages." (PMID 38824526, 2024).
Herpes simplex infection (1 paper, 2022). "The KEGG pathway analysis highlighted that a large number of genes that were up-regulated after infection with V2 were the same as those upregulated in response to Herpes simplex infection (genes Myd88, Irf7, H2-Q7, Casp8, Tlr3, Daxx, C3, H2-Aa, Oas2, Oas3, H2-T22, H2-T23 and Cd74)." (PMID 35458422, 2022).
herpetic keratitis (1 paper, 2019). "While complement C3 and antigen-specific CD4+ T cells appear to coordinate corneal sensation loss in herpetic keratitis, it remained to be determined whether this phenomenon was specific to HSV-1 infection." (PMID 31414985, 2019).
HIV-1 infection (1 paper, 2022). The type species of lentivirus and the etiologic agent of acquired immunodeficiency syndrome (AIDS). "Indeed, the lack of virus control by the 2219 KA mutant, which is unable to bind C1q and generate C3d, implies a role of the C3 complement activity in controlling HIV-1 infection." (PMID 34986207, 2022).
Hyperbilirubinemia (1 paper, 2024). An increased amount of bilirubin in the blood. "Laboratory findings indicative of CIHA include indicators associated with hemolytic anemia, such as decreased hemoglobin, reduced haptoglobin levels, elevated LDH, and hyperbilirubinemia, and immunological indicators suggestive of immune-mediated hemolysis like a positive DAT for C3 and/or IgG/IgM." (PMID 39840085, 2024). "The current diagnosis of DIIHA relies mainly on laboratory tests, with patients typically presenting hemolytic manifestations such as decreased hemoglobin levels and hyperbilirubinemia, along with positive direct anti-human globulin tests (DAT) for anti-C3 and/or IgG/IgM." (PMID 39840085, 2024).
hyperthyroidism (1 paper, 2023). Overactivity of the thyroid gland resulting in overproduction of thyroid hormone and increased metabolic rate. "A recent case in 2022 described a 29-year-old woman who presented with a painful and pruritic rash with signs and symptoms of hyperthyroidism including biochemical evidence of hyperthyroidism with positive TPO antibodies, positive TSH receptor antibodies and low complement C3 levels." (PMID 37251685, 2023).
hypokalaemia (1 paper, 2009). "Increased ammoniogenesis in the renal cortex during hypokalaemia leads to the amination of C3, with consequent activation of the alternative complement pathway and deposition of protein in the tubule." (PMID 19144110, 2009).
IgA Deficiency (1 paper, 2013). "We report a novel homozygous mutation in the C3 gene in a patient with concomitant selective IgA deficiency who presented with a marked clinical improvement after vaccination against S. pneumoniae." (PMID 22996269, 2013). "As mentioned, in addition to C3 deficiency the patient showed selective IgA deficiency (sIgAD)." (PMID 22996269, 2013).
IgA pemphigus (1 paper, 2022). Immunoglobulin A (IgA) pemphigus is a group of newly characterized immune-mediated intraepidermal blistering skin diseases. "Second, in DIF studies, the positive rates of deposition of IgG and C3 in the intercellular space of the epidermis in IgA pemphigus are 20.5% and 13.6%, respectively." (PMID 35625932, 2022).
inactive (1 paper, 2021). "The levels of iC3b and the iC3b/C3 ratio are higher in SLE patients than in normal healthy subjects, and the SLE patients with active disease have iC3b and iC3b/C3 ratio higher than patients with inactive disease." (PMID 33569681, 2021).
infectious anterior uveitis (1 paper, 2023). An infectious disease involving a pathogenic inflammatory response in the anterior uvea. "Quantitative real-time PCR was performed for the candidate genes, i.e., C3 and CFH, in the peripheral leukocytes of patients with non-infectious anterior uveitis and control subjects." (PMID 38187376, 2023).
infectious posterior uveitis (1 paper, 2023). "Quantitative real-time PCR for the candidate genes, i.e., C3 and CFH, in the peripheral leukocytes showed an upregulation of both C3 and CFH genes (FC-4.5 ± 0.8; * p = 0.04 and FC-7.09 ± 1.1; *p = 0.04 respectively) in the patients with non-infectious posterior uveitis as compared to controls." (PMID 38187376, 2023).
invasive carcinoma (1 paper, 2022). A carcinoma that is not confined to the epithelium, and has spread to the surrounding stroma. "We found that cathepsin L1, serpin B12 and mucin-19 were highly expressed in mice at the initial stage of disease, whereas Ig Alpha Chain C Region (IGHA) and Complement C3 were enriched in animals with invasive carcinoma." (PMID 35798767, 2022).
iron overload (1 paper, 2019). "In adults, iron overload is associated with increases in complement C3 and C-reactive protein (CRP), an acute phase reactant in inflammation and infection and regulated by IL-6." (PMID 30836628, 2019).
ischemic cardiomyopathy (1 paper, 2024). Ischemic cardiomyopathy is a cardiomyopathy in which a weakness in the muscle of the heart due to inadequate oxygen delivery to the myocardium with coronary artery disease being the most common cause. "Among them, C3 AGT + Fibroblasts had the highest percentage of ischemic cardiomyopathy (RM), and coincidentally ICM had a worse prognosis." (PMID 38799173, 2024).
juvenile idiopathic arthritis (1 paper, 2023). Juvenile idiopathic arthritis (JIA) is the term used to describe a group of inflammatory articular disorders of unknown cause that begin before the age of 16 and last over 6 weeks. "For example, Juvenile idiopathic arthritis (JIA) patients’ T cells have increased intracellular C3." (PMID 36969185, 2023).
kidney stone (1 paper, 2023). "C3 and C5 inhibitors might contribute to attenuate the complement-driven inflammation in kidney stone formation and recurrence." (PMID 36932340, 2023).
Leukocyte-Adhesion Deficiency Syndrome (1 paper, 2022). Rare, autosomal recessive disorder caused by deficiency of the beta 2 integrin receptors (RECEPTORS, LEUKOCYTE-ADHESION) comprising the CD11/CD18 family of glycoproteins. "This intrinsic C3 expression in T cells is important, as T cells lacking CD11a (part of LFA-1 heterodimer together with CD18), from the patients with leukocyte adhesion deficiency syndrome, do not upregulate C3 and, therefore, have defective TH1responses." (PMID 35860237, 2022).
limb ischemia (1 paper, 2013). A ischemia that involves the limb. "We selected complement C3 for further validation by western blotting and showed that the complement C3 expression in human serum significantly decreased from 1 h to 24 h after transient limb ischemia." (PMID 24363825, 2013). "It is concluded that transient limb ischemia alters the serum protein expression profile in human being, and that reduction of serum contents of complement C3 and vitronectin may represent an important part of the mechanism whereby RIPC confers its protection." (PMID 24363825, 2013). "Furthermore, we confirmed the changes of three proteins of complement C3, vitronectin (75 KDa), and apoA-I after transient limb ischemia by western blotting." (PMID 24363825, 2013).
Livedo reticularis (1 paper, 2025). A condition characterized by a reticular or fishnet pattern on the skin of lower extremities and other parts of the body. "No abnormalities in CH50 C3 and C4 testing were found in a patient presenting with livedo reticularis." (PMID 41150416, 2025).
Lyme borreliosis (1 paper, 2014). "A similar reliance on TLR/MyD88-dependent responses for pathogen clearance may explain the effects of complement component C3 deficiency on the course of murine Lyme borreliosis." (PMID 24967215, 2014).
macrocytic anemia (1 paper, 2026). Anemia that is characterized by increased red blood cell volume. "We report a 78-year-old woman who presented with fatigue, macrocytic anemia, reticulocytosis, elevated lactate dehydrogenase, low haptoglobin, indirect hyperbilirubinemia, a direct antiglobulin test positive for C3 and negative for IgG, and a cold agglutinin titer of 1:320." (PMID 42110104, 2026).
male infertility (1 paper, 2023). The inability of the male to effect fertilization of an ovum after a specified period of unprotected intercourse. "A total of five proteins (PFS males) have been used as potential markers of male infertility, namely B2M, complement-3 (C3), CFB, VNN2, and CTSS." (PMID 37969811, 2023).
Meniere disease (1 paper, 2014). A disease of the inner ear (labyrinth) that is characterized by fluctuating sensorineural hearing loss; tinnitus; episodic vertigo; and aural fullness. "However, evidence for inner ear pathology is insufficient, even though histopathological studies of the human temporal bone have demonstrated that patients with Meniere's disease have C3 and C1q deposits in their inner ear." (PMID 25330336, 2014).
metastatic colorectal cancer (1 paper, 2016). "Moreover, the data indicate that the excessive collagen degradation (C1M, C3M and C4M) and formation (Pro-C3) observed in metastatic colorectal cancer patients could play a role in cancer pathogenesis, either as a driver of tumour progression or by being a consequence hereof." (PMID 27465284, 2016).
migraine (1 paper, 2024). "Novel proteomics analysis revealed that the expression levels of complement C3 were higher in patients with migraine than in healthy volunteers or during pain than in the pain-free period." (PMID 37450927, 2024). "Therefore, it can be concluded that the C3/C3aR complement-activated astrocyte-microglia crosstalk is the core of neuroinflammation in a mouse model of CNS inflammatory diseases, such as migraine." (PMID 37450927, 2024).
Mitral stenosis (1 paper, 2014). An abnormal narrowing of the orifice of the mitral valve. "This may be the reason for the lower abundances of C3, C4A, C4B and C4b binding protein α chain observed in Mitral Stenosis patients." (PMID 25379033, 2014).
MODY (1 paper, 2020). "In contrast, complement-3 (C3) levels, an inflammatory protein with antifibrinolytic properties, were lower in the MODY group compared with T2DM (0.58 ± 0.09 vs 0.80 ± 0.1, p < 0.01)." (PMID 33334146, 2020).
mycobacteriosis (1 paper, 2020). "In these experiments, we showed a reduction of mycobacteriosis in vaccinated fish and suggested that the innate immune response mediated by the C3 pathway activated through TLR-AKR2-IL-1β and other proinflammatory cytokines acted as the protective mechanism against infection." (PMID 32344637, 2020).
nasal polyps (1 paper, 2020). "Expression of complement factors, including C3, C5, and the anaphylatoxin receptors, was analyzed in nasal polyp tissue samples, the corresponding inferior turbinates, and healthy controls using transcriptomic methods and protein measurements." (PMID 32724828, 2020). "Distinct patterns of complement expression were found in nasal polyps compared to controls, characterized by an increased C3 activation and an increase in C3aR-bearing cells." (PMID 32724828, 2020). "That would propose that possibly activated B cells, becoming larger during activation and differentiation, contain detectable higher intracellular C3 levels in nasal polyps." (PMID 32724828, 2020). "Our data suggest a prominent role for the C3-C3aR-axis in nasal polyps and, for the first time, describe a B cell population containing high levels of intracellular C3, suggesting a new role of B cells in the maintenance of the inflammation by complement." (PMID 32724828, 2020). "Here, we aim to study complement signatures, especially the C3-C3aR axis, and focus on cellular sources and targets in nasal polyps." (PMID 32724828, 2020). "In summary, we have shown a C3-C3aR axis occupation in nasal polyps together with an augmented intracellular C3 repertoire in B cells which could refer to a prominent role for complement in disease progression." (PMID 32724828, 2020). "We could demonstrate immunohistochemical C3 deposition at the epithelium and in the lumen in nasal polyps, but also for the inferior turbinate." (PMID 32724828, 2020). "Besides low intracellular C3-expression levels for lymphocytes in general, we could identify an enlarged B lymphocyte population in nasal polyps displaying high amounts of intracellular C3." (PMID 32724828, 2020). "Therefore, although an increased complement activation might occur at epithelial areas, the intracellular C3 amount is not enhanced in epithelial cells of nasal polyps." (PMID 32724828, 2020).
nasopharyngeal carcinoma (1 paper, 2025). A carcinoma arising from the nasopharyngeal epithelium. "Complement C3 shows potential as a biomarker for early diagnosis; however, further research is required to validate its association with cancer, particularly nasopharyngeal carcinoma." (PMID 40565234, 2025).
neural tube defect (1 paper, 2021). A congenital defect characterized by failure of the neural tube to close completely; this results in the presence of openings in the brain or spinal cord. "C3 protein is downregulated significantly in the serum of pregnant women with neural tube defects compared with the women carrying normal fetuses during pregnancy." (PMID 34827915, 2021). "Neural tube defects in pregnant women lead to downregulation of the C3 protein in the serum compared with normal pregnant women." (PMID 34827915, 2021).
nonalcoholic steatohepatitis (1 paper, 2008). "In addition, the analyses of global hepatic gene expression in histologically progressive nonalcoholic steatohepatitis revealed down-regulated genes for maintaining mitochondrial function and up-regulated genes of C3 and hepatocyte-derived fibrinogen-related protein." (PMID 18307821, 2008).
oesophageal adenocarcinoma (1 paper, 2021). "Previously, our group demonstrated that C3 mRNA expression was significantly increased in tumour biopsies of oesophageal adenocarcinoma patients with a subsequent poor response to neoadjuvant chemoradiotherapy (neo-CRT)." (PMID 33802004, 2021). "Similarly, in a miR-187 overexpressing oesophageal adenocarcinoma (OAC) cell line, C3 mRNA was downregulated, suggesting negative regulation of C3 by miR-187." (PMID 33802004, 2021).
Opportunistic infection (1 paper, 2019). An infection that is caused by a pathogen that would generally not be able to cause an infection in a host with a normal immune system. "Similarly, altered expression of L-selectin, a key factor of lymphocyte adhesion and extravasation into secondary lymphoid organs might explain the decreased immune response and opportunistic infections in the absence of C3." (PMID 30941132, 2019).
ovarian dysfunction (1 paper, 2023). The inability of the ovaries to function. "Among the genes we identified through coexpression of three datasets, PNPLA3, MVD, MMP9, oncostatin M (OSM), LCK, triggering receptor expressed on myeloid cells 1 (TREM1), FADS2, proprotein convertase subtilisin/kexin type 9 (PCSK9), and C3 are involved in lipid metabolism and ovarian dysfunction." (PMID 37537636, 2023).